NOS3 (nitric oxide synthase 3)
Diseases named in the same sentence as NOS3 in open-access papers (continued):
Sharing a sentence is not in itself a finding about the gene and the disease.
autoimmune disease (2 papers, 2022 to 2023). A disorder resulting from loss of function or tissue destruction of an organ or multiple organs, arising from humoral or cellular immune responses of the individual to their own tissue constituents. "NOSTRIN connects to another nitric oxide gene, NOS3, RNF115 to the RAS oncogene family member RAB7A, while SPRR2A connects with EVPL (associated with squamous cell cancer and autoimmune disease)." (PMID 38030619, 2023).
bladder cancer (2 papers, 2017 to 2025). "The study identified that the NOS3 promoter polymorphism −786T>C (rs2070744) may influence bladder cancer risk, while Glu298Asp (rs1799983) carries no increased bladder cancer risk." (PMID 39859471, 2025).
cerebral palsy (2 papers, 2011 to 2023). A group of disorders affecting the development of movement and posture, often accompanied by disturbances of sensation, perception, cognition, and behavior. "Numerous studies have investigated the association of polymorphisms in the NOS3 gene with the occurrence of cerebral palsy, but only two studies have confirmed it." (PMID 37893168, 2023). "A number of studies have investigated the association of polymorphisms in NOS3 gene with the occurrence of cerebral palsy, however only two studies have confirmed it." (PMID 21674837, 2011). "So far, two studies have shown a correlation of NOS3 -922A (rs1800779) polymorphism with cerebral palsy in preterm infants." (PMID 21674837, 2011).
cervical cancer (2 papers, 2023). A primary or metastatic malignant neoplasm involving the cervix. "Although we were not able to associate NOS3 with cancer, phytochemical-induced apoptosis has been linked to the NO signaling pathway activation in cervical cancer." (PMID 37891885, 2023).
diabetic cardiomyopathy (2 papers, 2023 to 2024). Diabetic cardiomyopathy is a disorder of the heart muscle in people with diabetes. "The ICM LV vs RV KEGG protein analysis revealed up-regulation of fluid sheer stress and diabetic cardiomyopathy principally due to the up-regulation of endothelial nitric oxide synthase 3 (NOS3, seven-fold), caveolin 1 (CAV1)." (PMID 39702518, 2024).
dilated cardiomyopathy (2 papers, 2013 to 2023). Cardiomyopathy which is characterized by dilation and contractile dysfunction of the left and right ventricles. "It is also reported that the genetic heterogeneity of endogenous NO production through NOS3 genetic variations may affect left ventricular remodeling, which is an important pathological feature in dilated cardiomyopathy." (PMID 23923002, 2013).
endometrial cancer (2 papers, 2016 to 2025). Primary or metastatic malignant neoplasm involving the endometrium (mucous membrane that lines the endometrial cavity). "Interestingly, both the NOS3 polymorphism G894T and variable number tandem repeats polymorphism in the intron 4 are proposed as factors of susceptibility for endometrial cancer associated with increased nitric oxide synthesis." (PMID 27469435, 2016).
gastric adenocarcinoma (2 papers, 2025). "For instance, NOS3 is highly expressed in stomach adenocarcinoma and correlates with poor patient prognosis." (PMID 41233831, 2025). "NOS3 (eNOS) expression is significantly higher in gastric adenocarcinoma tissues than in normal tissues." (PMID 41346571, 2025).
laryngeal carcinoma (2 papers, 2016 to 2021). Carcinoma that arises from the laryngeal epithelium. "No reports are available in current literature that investigates G894T polymorphism in exon 7 of the NOS3 gene and oxidative protein damage in laryngeal cancer." (PMID 26682008, 2016). "Moreover, the NOS3 polymorphisms play crucial roles in the molecular mechanism of cancers and clinical survivals of patients undergoing cancers, including laryngeal cancer." (PMID 34986125, 2021). "Allelic variation of NOS3 may influence an individual's risk of laryngeal cancer (LC)." (PMID 26682008, 2016).
laryngeal squamous cell carcinoma (2 papers, 2021 to 2022). A squamous cell carcinoma that arises from the larynx.
liver cancer (2 papers, 2017 to 2023). An epithelial or non-epithelial malignant neoplasm that arises from the liver. "In liver cancer cells, the overexpression of NOS2 and NOS3 induces a transition between apoptosis and autophagy by disrupting the Beclin 1/Vps34 association and increasing the Bcl-2/Beclin 1 interaction." (PMID 37958916, 2023).
lung adenocarcinoma (2 papers, 2020 to 2023). A carcinoma that arises from the lung and is characterized by the presence of malignant glandular epithelial cells. "This study aims to show the contribution and effects of various gene polymorphisms in the NOS3 and CTH genes, as well as their associations with lung adenocarcinoma." (PMID 38107574, 2023).
metastatic colorectal cancer (2 papers, 2021 to 2023). "Furthermore, NOS3 levels were found to be inversely associated with progression-free survival and overall survival (OS) in patients with metastatic colorectal cancer." (PMID 37894904, 2023). "Among metastatic colorectal cancer patients, NOS3 inversely correlated with disease-progression-free survival and overall survival." (PMID 34885088, 2021).
Myocardial fibrosis (2 papers, 2021 to 2025). "MiR-21 can inhibit apoptosis and inflammation by targeting KBTBD7, regulate angiogenesis through STRN/NOS3, and promote myocardial fibrosis through the TGF-β/Smad7 signaling pathway." (PMID 35111829, 2021).
osteonecrosis (2 papers, 2017 to 2021). A none disease characterized by death of bone tissue due to a lack of blood supply. "Genetic mutation of alcohol-metabolizing enzyme genes has been associated with alcohol-induced osteonecrosis and polymorphism of NOS3, ABCB1 and IL23R gene are related with developing osteonecrosis." (PMID 28422712, 2017).
osteosarcoma (2 papers, 2021 to 2024). A usually aggressive malignant bone-forming mesenchymal neoplasm, predominantly affecting adolescents and young adults. "Protection against osteosarcoma was solely associated with EDN1 SNPs, while PCa was mainly studied in relation to NOS3 SNPs." (PMID 38785560, 2024).
placental insufficiency (2 papers, 2015 to 2018). Failure of the placenta to deliver an adequate supply of nutrients and oxygen to the fetus. "We also demonstrated that the changes observed in response to placental insufficiency are associated with changes of the epigenetic signatures at the NOS3 gene locus." (PMID 25699114, 2015). "Similar to 5hmeC levels, we found increased levels of H3K9ac and H2A.Zac adjacent to the TSS in patients with high-NOS3 mRNA levels who suffered from intrauterine placental insufficiency." (PMID 25699114, 2015). "Apparently, a rapid NOS3 self-limiting response upon ectopic triggers co-exists with longer termed expression changes in response to placental insufficiency involving differential epigenetic signatures." (PMID 25699114, 2015). "Importantly, we were also able to demonstrate that 27 nt-ncRNA levels correlated with NOS3 mRNA levels in patients with normal placental flow whereas this relationship seemed to be dissolved in patients with severe placental insufficiency." (PMID 25699114, 2015). "NOS3 and STAT3 mRNA levels were elevated in HUAEC of patients who suffered from placental insufficiency." (PMID 25699114, 2015). "To further analyse the dynamic of NOS3 and STAT3 expression, we made use of an in vitro cell culture model simulating placental insufficiency by depriving HUAEC of oxygen for 24 h." (PMID 25699114, 2015).
psychosis (2 papers, 2011 to 2020). "Because rare variants with functional effects in NOS3 have the possibility of influencing susceptibility of METH-induced psychosis, further investigations including mutation scan using large samples will be required." (PMID 21886581, 2011). "Based on this evidence, we suspected that NOS3 might be related to the pathophysiology of METH-induced psychosis, and conducted a genetic association analysis of six tagging SNPs, including two functional SNPs, in NOS3 and METH-induced psychosis in the Japanese population." (PMID 21886581, 2011). "However, there are few genetic association studies between NOS3 and psychotic disorders." (PMID 21886581, 2011). "In this study, we performed a genetic association study based on LD between NOS3 and METH-induced psychosis." (PMID 21886581, 2011). "In conclusion, we suggest that NOS3 might not contribute to the risk of METH-induced psychosis in the Japanese population." (PMID 21886581, 2011). "In conclusion, our results suggest that NOS3 does not play a major role in METH-induced psychosis in the Japanese population." (PMID 21886581, 2011).
scleroderma (2 papers, 2022 to 2026). Scleroderma is a rare autoimmune connective tissue disorder characterized by abnormal hardening of the skin and, sometimes, other organs. "The MMP9 risk genotype did not correlate with scleroderma-specific autoantibodies, while the NOS3 GG genotype was associated with lower serum levels of anti-collagen IV antibodies (p = 0.039)." (PMID 41596747, 2026).
skin cutaneous melanoma (2 papers, 2021 to 2022). "Among the hyper-altered cancer types, uterine corpus endometrial carcinoma, skin cutaneous melanoma, and lung squamous cell carcinoma were the most prominent cancer types, which was probably due to the high mutation frequencies of INSR, ACE, and NOS3." (PMID 35513851, 2022). "The mutations of NOS3 and ACE have prognostic potential for the overall survival of adrenocortical carcinoma and skin cutaneous melanoma patients, respectively." (PMID 35513851, 2022). "NOS3 mRNA expression in 6 of 28 tumor types, rectum adenocarcinoma (READ), STAD, PAAD, ovarian serous cystadenocarcinoma (OV), skin cutaneous melanoma (SKCM), head and neck squamous cell carcinoma (HNSC), was much higher than that in corresponding normal tissues, with statistical significance." (PMID 33747912, 2021).
ST Elevation Myocardial Infarction (2 papers, 2019 to 2025). A myocardial infarction that produces elevation in the ST segments of the ECG. "Materials and methods: NOS3 (rs1799983) and DDAH2 (rs805305) single nucleotide polymorphisms (SNPs) were analyzed in 148 ST-elevation myocardial infarction (STEMI) patients and 75 healthy subjects (control) using polymerase chain reaction-restriction fragment length polymorphism (PCR-RFLP)." (PMID 40144407, 2025).
steatosis (2 papers, 2019 to 2022). Increased lipid within the cytoplasm of cells. "Under special high-fat diet conditions, ApoE/NOS3−/− mice developed severe hepatocyte steatosis and hepatocyte enlargement." (PMID 36360235, 2022). "In addition, serum total cholesterol (TC) and low-density lipoprotein (LDL) levels in the blood were abnormally elevated, steatosis was observed in the liver cells, and atherosclerotic lesions were observed in the aortic vessels in ApoE/NOS3−/− adult mice." (PMID 36360235, 2022). "RUNX1 target genes, CCL2 and PIK3CA significantly correlated to NAS, steatosis, inflammation grade and fibrosis score, NOS3 to NAS and inflammation grade and PRKCE to NAS and steatosis grade." (PMID 31635436, 2019).
Ventricular arrhythmia (2 papers, 2011 to 2021). "Further study is necessary to fine-map these loci, identify causative variants, and elucidate their impact on CACNA1C and NOS3 function or levels, signaling, L-type calcium current, and whether they ultimately affect development of ventricular arrhythmias." (PMID 21658281, 2011). "Reduction or elimination of NOS3-produced nitric oxide, which by itself attenuates β-adrenergic stimulation of L-type calcium channel currents, causes higher influx of calcium ions which can lead to two potent triggers of ventricular arrhythmias: early and delayed afterdepolarizations." (PMID 21658281, 2011).
acute myeloid leukemia (1 paper, 2021). Acute myeloid leukemia (AML) is a group of neoplasms arising from precursor cells committed to the myeloid cell-line differentiation. "In tumor tissues, NOS3 expression levels varied from 9.85 (stomach adenocarcinoma, STAD) to 5.071 (acute myeloid leukemia, LAML)." (PMID 33747912, 2021).
adrenocortical carcinoma (1 paper, 2022). "The mutation of NOS3 was positively correlated with the overall survival of adrenocortical carcinoma patients." (PMID 35513851, 2022).
alcohol (1 paper, 2017). "This study provides evidence for three alcohol-induced ONFH susceptibility genes (NOS3, ABCB1 and IL23R) in Chinese males and polymorphisms of them may be associated with alcohol-induced ONFH risk." (PMID 28422712, 2017).
aneurysmal disease (1 paper, 2015). "Furthermore, examination of the proximal aorta of Notch1+/−; Nos3−/− mice reveals elastic fiber degradation, a trend toward increased matrix metalloproteinase 2 expression, and increased smooth muscle cell apoptosis, features characteristic of aneurysmal disease." (PMID 25914885, 2015).
Aortic dissection (1 paper, 2020). Aortic dissection refers to a tear in the intimal layer of the aorta causing a separation between the intima and the medial layers of the aorta. "Moreover, a small patient study reported that polymorphisms in Nos3 were associated with aortic dissections in patients with thoracic aortic aneurysms." (PMID 32801116, 2020). "Future studies should look more specifically into the mortality rate related to aortic dissection in Nos3−/− mice to better understand the timing and risks involved in the development of an aortic dissection." (PMID 32801116, 2020). "The mortality rate in humans is known to increase to 70% within 48 h after aortic dissection and Nos3−/− mice might face an equal rapid increase of mortality rate after the onset of aortic dissection." (PMID 32801116, 2020).
ascending aortic aneurysm (1 paper, 2020). "Later studies by the same group, however, reported that Notch1 haploinsufficiency in 129SV mice also causes ascending aortic aneurysm, making the role of Nos3 in aortopathy less clear." (PMID 32801116, 2020).
Ascending aortic dissection (1 paper, 2020). A separation of the layers within the wall of the ascending aorta. "Decreased elastin concentrations within the aortic wall are strongly correlated with decreased expression of Fbln5 in patients with ascending aortic dissection, similar to our findings using Nos3−/− mice." (PMID 32801116, 2020).
B-cell non-Hodgkin lymphoma (1 paper, 2023). The most common type of non-Hodgkin lymphoma. "The evaluation of NOS isoform expression levels in B-cell non-Hodgkin lymphoma tissues showed NOS1 more frequently expressed compared with NOS2 and NOS3 (94% of cases vs. 87% vs. 6%, respectively)." (PMID 37345090, 2023).
bacterial pneumonia (1 paper, 2014). Acute infection of the lung parenchyma caused by bacteria (e.g., Streptococcus pneumoniae, Haemophilus influenzae, Chlamydia pneumoniae, Mycoplasma pneumoniae, and Legionella pneumophila). "The data identify a novel mechanism for host defense via NOS3 and suggest a potential therapeutic strategy to reduce secondary bacterial pneumonia after influenza." (PMID 25317947, 2014). "To begin testing of the translational potential of targeting NOS3, we first tested whether local delivery of estrogen to the lungs would improve resistance to bacterial pneumonia." (PMID 25317947, 2014).
basophilic leukemia (1 paper, 2016). "NOS1, inducible NOS (NOS2) and NOS3 have been found in human mast cell (HMC)-1 cell line, NOS3 has been found in rat basophilic leukemia RBL-2H3 cell line and NOS2 is expressed in P815 mouse mastocytoma cell line." (PMID 27538454, 2016).
bipolar disorder (1 paper, 2011). A disorder of the brain that causes unusual shifts in mood, energy, activity levels and the ability to carry out day-to-day tasks. "They suggested that a haplotype including two functional SNPs (rs2070744, rs1799983) in NOS3 may influence the susceptibility of bipolar disorder." (PMID 21886581, 2011).
Candidemia (1 paper, 2019). A form of invasive candidiasis where species of CANDIDA are present in the blood. "Compared to wild type mice, Nos3-/- mice showed significantly higher survival of candidemia caused by Candida albicans SC5314." (PMID 31671151, 2019). "Conversely, the general NOS inhibitor NG-nitro-L-arginine methyl ester increased virulence in the mouse candidemia model, suggesting that iNOS contributes to the protective mechanism in infected Nos3-/- mice." (PMID 31671151, 2019).
candidiasis (1 paper, 2019). Infection with the organism Candida. "Nos3-/- mice exhibit attenuated pro-inflammatory responses to Candida infection in the kidney." (PMID 31671151, 2019). "Confirming our initial day 3 PI, intracellular flow, Nos3-/- mice showed significantly higher Th9 subset (CD4+IL-9+) and Th2 subset (CD4+IL-4+) induction due to dissemination candidiasis at days 2–6 PI." (PMID 31671151, 2019).
cholestasis (1 paper, 2016). Impairment of the bile flow caused by obstruction within the liver, or outside the liver in the bile duct system. "Cholestasis is a disorder that is associated with oxidative damage and with the NOS-3 expression deregulation." (PMID 27490694, 2016). "Recently, we have shown that transcription factor (TF) SP1 negatively regulates NOS-3 expression during GCDCA-induced cholestasis through direct binding to the NOS-3 promoter (pNOS-3) in an oxidative stress dependent manner." (PMID 27490694, 2016). "Here, we studied the involvement of new proposed TF binding sites (TFBS) for AP-1, GATA-1 and GATA-4 in the regulation of NOS-3 expression during experimental cholestasis in the human hepatocarcinoma cell line HepG2." (PMID 27490694, 2016). "In the present study, we aimed to investigate the role of transcription factor (TF) AP-1 on the NOS-3 deregulation during GCDCA-induced cholestasis." (PMID 27490694, 2016). "Our data provide direct evidence for the involvement of AP-1 in the NOS-3 expression regulation during cholestasis and define a critical role for NOS-3 in regulating the expression of cyclin D1 during the cell damage induced by bile acids." (PMID 27490694, 2016). "This, together with the fact that no expression of NOS-2 was detected in our experimental model of cholestasis, suggests that NOS-3 regulation by AP-1 is a key process involved in the hepatocellular damage during cholestasis." (PMID 27490694, 2016). "In a model of experimental cholestasis in vivo, the observed hepatocellular damage was associated with the inhibition of NOS-3 expression and the activation of TFs cJun and cFos (data not shown)." (PMID 27490694, 2016). "However, since these two compounds have also been described as SP1 inhibitors with antioxidant properties, and both, SP1 and oxidative stress, are related to NOS-3 expression regulation during cholestasis, these results could not be directly attributed to the inhibition of AP-1." (PMID 27490694, 2016).